RNU6-1003P (RNA, U6 small nuclear 1003, pseudogene)
Gene: Small nuclear RNA gene on chromosome 5 (17,240,611 to 17,240,715, forward strand). Ensembl gene ENSG00000252908.
Homologues: Orthologues: chimpanzee U6 (97% identical), macaque U6 (93% identical), pig U6 (86% identical), pig U6 (76% identical), rat LOC120098445 (60% identical). Paralogues in human: RNU6-1060P (87% identical), RNU6-1122P (86% identical), RNU6-41P (86% identical), RNU6-15P (85% identical), RNU6-31P (85% identical), RNU6-379P (85% identical), RNU6-44P (85% identical), RNU6-748P (85% identical), RNU6-842P (85% identical), RNU6-1019P (84% identical), RNU6-1029P (84% identical), RNU6-125P (84% identical), and 1286 more.